CCK (cholecystokinin)
Diseases named in the same sentence as CCK in open-access papers (continued):
Sharing a sentence is not in itself a finding about the gene and the disease.
ischemia (1 paper, 2025). A hypoperfusion of the BLOOD through an organ or tissue caused by a PATHOLOGIC CONSTRICTION or obstruction of its BLOOD VESSELS, or an absence of BLOOD CIRCULATION. "IC associated with OSS may result from both the rapid shift of intravascular fluid into the colonic lumen, causing inadequate perfusion, and the magnesium sulfate in OSS, which stimulates colonic motility via cholecystokinin and prostaglandins, potentially leading to ischemia." (PMID 41021559, 2025).
islet cell tumor (1 paper, 2017). "Recently, a metastastic islet cell tumor was found to cause a specific CCKoma syndrome, suggesting that circulating CCK may be a useful tumor marker." (PMID 28450850, 2017).
Lissencephaly (1 paper, 2016). A spectrum of malformations of cortical development caused by insufficient neuronal migration that subsumes the terms agyria, pachygyria and subcortical band heterotopia. "Interestingly, deletion of dystroglycan in postmitotic neurons does not cause neuronal ectopia but affects functional innervation of cholecystokinin-positive basket cell terminals on pyramidal neurons, supporting the pathological complexity of type II lissencephaly." (PMID 27916859, 2016).
liver tumours (1 paper, 2013). "The majority of liver tumours express cholecystokinin (CCK-B) receptors and are able to process gastrin (G) as far as pro-G and G-gly (precursor forms) and this may be associated with tumour proliferation." (PMID 24137355, 2013). "The majority of liver tumours express cholecystokinin (CCK-B) receptors and are able to process gastrin (G) as far as pro-G and G-gly (the precursor forms), which may be associated with tumour proliferation." (PMID 24137355, 2013).
low grade glioma (1 paper, 2025). A grade I or grade II glioma arising from the central nervous system. "Interestingly, our DEG analysis also defined CCK and NRGN gene expression differences between C1 and C2 LGG subgroups as expected with the weaker expression in cerebellar low-grade gliomas (C2)." (PMID 40382536, 2025).
malaise (1 paper, 2022). A feeling of general discomfort or uneasiness, an out-of-sorts feeling. "In control experiments, silencing duodenal CCK-labeled neuropod cells with 532-nm light did not cause malaise, as neither locomotor activity during the assay nor chow or water intake in the following 24 h were affected." (PMID 35027761, 2022).
Myocardial fibrosis (1 paper, 2023). "However, CCK-8 administration, a sulfated carboxyterminal octapeptide and a major bioactive segment of CCK improved the ventricular function and attenuated myocardial fibrosis and ventricular remodeling in an animal study of myocardial infarction." (PMID 36834796, 2023).
myositis (1 paper, 2013). "The lack of I-cell hyperplasia in wild-type mice at day 20 p.i. and the presence of the second phase of hypophagia in CCKlacZ mice confirm this extraintestinal period of hypophagia during myositis as CCK independent." (PMID 23349631, 2013).
neuropathy (1 paper, 2021). A disorder affecting the nervous system that manifests with pain, tingling, numbness, and/or muscle weakness. "Thus, it seems that the increased CCK peptide levels may be responsible for the decrease in opioid efficacy after neuropathy." (PMID 34903982, 2021).
opioid dependence (1 paper, 2018). "More evidence is needed to ascertain the role of CCK receptors, especially CCK1R, in the modulation of CCK–opioid system interactions in opioid dependence." (PMID 30147637, 2018).
Peptic ulcer (1 paper, 2023). The term peptic ulcer refers to acid peptic injury of the digestive tract, resulting in mucosal break reaching the submucosa. "CCK secretion by a PNET is also very rare, though it can present with symptoms similar to Zollinger-Ellison syndrome such as a peptic ulcer, in addition to weight loss and diarrhea." (PMID 37046665, 2023).
prediabetes (1 paper, 2019). "Individuals with prediabetes or type 2 diabetes may instead depend more on dietary fiber intake to stimulate satiety and improve glycemic control, as well as other satiety hormones, such as CCK, GLP-1, and PYY, which are released mainly in response to fats and protein reaching the small intestine." (PMID 30861997, 2019).
preeclampsia (1 paper, 2021). Preeclampsia is a hypertensive disorder of pregnancy that is characterized by new-onset hypertension with proteinuria presenting after 20 weeks of gestation, and depending on mild or severe forms may initially present with severe headache, visual disturbances, and hyperreflexia. "Finally, cholecystokinin is one of the most highly upregulated genes in early placentas from women who later developed preeclampsia compared with women who experienced a normal pregnancy; however, its role in the placenta has not been investigated." (PMID 34360662, 2021).
respiratory depression (1 paper, 2021). A decrease in ventilation secondary to impaired signals from the central nervous system. "CCK-8, applied centrally or systemically, has been observed to evoke various respiratory responses: stimulation, but also short-lived respiratory depression, even with episodes of prolonged apnea after the icv challenge." (PMID 34948415, 2021). "There are no data on whether CCK affects post-opioid respiratory depression." (PMID 34948415, 2021).
rhabdomyosarcoma (1 paper, 2015). A rare aggressive malignant mesenchymal neoplasm arising from skeletal muscle. "The first data demonstrating a relationship between CCK expression and EWS/FLI1 came from studies performed in heterologous systems: ectopic expression of EWS/FLI1 in the RD rhabdomyosarcoma cell line and in HeLa cells upregulated CCK mRNA levels." (PMID 26258070, 2015).
skin tumors (1 paper, 2022). "The simultaneous expression of CCK and CCK receptors implies that the CCK receptor‒mediated signaling operates in an autocrine or paracrine manner as a growth mechanism in these skin tumors." (PMID 36262666, 2022). "Next, we evaluated the expression levels of CCK and its receptors in several skin tumor cell lines." (PMID 36262666, 2022). "CCK is present in epidermal KCs; hence, CCK derived from these cells may contribute to the growth of skin tumors." (PMID 36262666, 2022).
stomach carcinoma (1 paper, 2013). "The expression of CCKsv, together with wild type CCK, was further confirmed by RT-PCR in human SK-N-MC and stomach carcinoma KATO-III cells." (PMID 23724068, 2013).
stress-related disorder (1 paper, 2013). Stress-related disorders are mental health disorders that are a result of an atypical response to both short and long-term anxiety due to physical, mental, or emotional stress. "Overall, there are evidence suggesting that CCK may be involved in both affective- and stress-related disorders." (PMID 23986909, 2013).
trauma (1 paper, 2023). "Moreover, the exocrine pancreatic enzyme production could be activated through central pathways in cases of head trauma, including increased vagal tone, release of activating hormones such as cholecystokinin and/or altered adrenergic stimulation." (PMID 37391848, 2023).
withdrawal syndrome (1 paper, 2012). "However, the induction of CPA by CCK-8 itself after morphine pretreatment was not significant, and CCK-8 could not precipitate the same morphine withdrawal syndrome as the opioid receptor antagonist." (PMID 22848639, 2012).
Zinc deficiency (1 paper, 2015). A deficiency of the essential metal Zinc; an essential cofactor for many enzymes. "In addition to processes associated with deleted genes, bioinformatic analysis of CCK gene interactome indicated that zinc deficiency might be a pathogenic mechanism in this case." (PMID 26523151, 2015).
tumor (41 papers, 1985 to 2026). "CEs are generated downstream of receptors involved in normal and tumour cell proliferation, such as the cholecystokinin (CCK2) receptor." (PMID 40723223, 2025). "CCK antagonists block tumor growth by inducing apoptosis in tumor cells, augmenting the activity of caspase 3, and reducing proteasome activity." (PMID 39063232, 2024). "Its ligands, gastrin and cholecystokinin (CCK), drive increased tumor growth and are often aberrantly upregulated in PDAC cells." (PMID 38790986, 2024). "Evidence from preclinical studies is most supportive of tumor-modulating roles for insulin, CCK, and Lcn2, whereas data are less conclusive for the adipokines leptin and adiponectin, despite correlations from human epidemiologic studies." (PMID 37648285, 2023). "In vivo and in vitro studies have revealed that the CCK/CCK receptor engagement is involved in the proliferation and survival of several tumor cells." (PMID 36262666, 2022). "The cholecystokinin (CCK) receptor is expressed in various types of tumors because CCK promotes the survival and proliferation of tumor cells." (PMID 36262666, 2022). "These antibodies can bind to gastrin peptides to prevent their interaction with the CCK-BRs on the surface of tumor cells." (PMID 34926305, 2021). "Peptides such as secretin, gastrin, bombesin, cholecystokinin, and vasoactive intestinal peptide are believed to promote the proliferation of tumor cells." (PMID 32056066, 2020). "Extensive investigations have demonstrated the expression of gastrin, CCK, and their receptors in a variety of tumor cells and tissues and their involvement in the regulation of cell proliferation and apoptosis, as well as the pathogenesis of cancer." (PMID 32210918, 2020). "With a radionuclide chelator attached to the N-terminus of CCK or gastrin peptide analogs, a variety of reagents have been created for tumor imaging and radiotherapy, including CCK-8, gastrin 10, mini-gastrin, gastrin dimers, and cyclic gastrin analogs." (PMID 29865257, 2018). "The method in which fatty acids accelerates tumor growth is partial mediated by the interaction of the gastrointestinal peptide cholecystokinin, CCK, and its receptor." (PMID 28294968, 2017). "The present knowledge about tumor expression of CCK was recently summarized in a review that also discussed measurements of CCK and proCCK in plasma as tumor markers." (PMID 28450850, 2017). "By investigating these potential mechanisms, we discovered new insights on how blocking the CCK-BR signaling pathway aids in remodeling the tumor microenvironment, the activity of T-cells, and the modulation of the gut microbiome to enhance the efficacy of immune checkpoint therapy." (PMID 41008842, 2025). "In addition, PET/CT imaging of tumor-bearing control group animals verified a CCK-2R-specific uptake of [68Ga]Ga-DOTA-CCK-66." (PMID 39392495, 2025). "CCK was expressed in 6 tumors, but only 1 tumor had strong and diffuse positivity." (PMID 40553402, 2025). "A note on reliability of CCK measurements will also be given before describing the perspective of pathophysiological involvement of CCK in metabolic disorders, gallbladder pathology, neuropsychiatric diseases, cardiac diseases, and various neoplasias." (PMID 40557463, 2025). "Furthermore, proglumide exhibits a direct anti-tumor effect by blocking upstream PI3K-AKT-mTOR signaling pathways through antagonism of the CCK-BR perhaps allowing for the use of a lower dose of ICI with fewer immune mediated side effects." (PMID 41008842, 2025). "Tumor formation could be monitored; treatment with proglumide could be performed to assess CCK-BR blockade’s effect on tumor growth." (PMID 38252699, 2024). "In this current investigation, we showed that treatment of mice with a CCK-BR antagonist, proglumide, could inhibit RIL-175 tumor growth, implying that this drug is blocking the actions of endogenous CCK or gastrin at the receptor." (PMID 36835036, 2023).
tumor (continued). "Indeed, we confirmed that CCK was endogenously expressed in β cells of obese tumor-bearing KCO mice and that transgenic β cell CCK expression was sufficient to promote Kras-driven ductal tumorigenesis." (PMID 37648285, 2023). "CCK promotes the proliferation and survival of tumor cells, and thus the blockade of the CCK receptor with its antagonists suppresses the proliferation and induces the apoptosis of tumor cells, leading to the inhibition of tumor growth in vivo." (PMID 36262666, 2022). "Thus, endogenous CCK and its receptor are important in tumor progression and metastasis of pancreatic cancer, particularly within the context of high fat consumption." (PMID 28294968, 2017). "It seemed gastrin played a more dominant role than CCK in stimulating tumor growth." (PMID 23077482, 2012). "When the same dose of CCK was given to animals receiving N-nitrosobis (2-oxopropyl)amine (BOP; 5 mg kg-1 weekly) there was a reduction in latency period and increase in induction rate of tumour development (CCK + BOP vs. BOP alone, 12 animals with tumours vs. 2 at 15 weeks; P less than 0.02)." (PMID 3966964, 1985). "Indeed, gastrin and CCK, as well as their receptors, are expressed in a variety of tumor cell lines, animal models, and human samples, and might contribute to certain carcinogenesis." (PMID 32210918, 2020). "Tumor imaging and PRRT have been extended to many other receptors such as Gastrin-releasing peptide/bombesin (GRP) and Cholecystokinin (CCK) in recent years." (PMID 23316341, 2012). "The one tumor with strong and diffuse positivity for CCK was negative for all other hormones." (PMID 40553402, 2025). "A tumour‐produced incretin could not be identified (we checked for GLP‐1, CCK, pro CCK and GIP), but somatostatin levels were markedly increased in the basal state (5 nmol/L, normal <0.1) and decreased during the glucose challenge." (PMID 31592116, 2019).
cancer (29 papers, 2008 to 2025). A tumor composed of atypical neoplastic, often pleomorphic cells that invade other tissues. "Interruption of this pathway with CRISPR knockout of the CCK-BR in pancreatic stellate cells significantly reduces the growth of cancer cells as well as the migration and proliferation of the fibroblasts." (PMID 41373844, 2025). "Expression and function profiles of gastrin, CCK, and their receptors in human cancer cell lines and tissues." (PMID 32210918, 2020). "Another line of evidence, the identification and characterization of the CCK2R splice variants and mutations, further confirmed the involvement of the gastrin and CCK system in cell proliferation and cancer pathogenesis." (PMID 32210918, 2020). "Cancer cells produce and secrete the neuropeptides CCK/gastrin, GRP and NMB, bradykinin, and vasopressin." (PMID 29262666, 2017). "Surprisingly, CCK secretion by the cancer cells was found to be induced by CTSB, suggesting that CCK and CTSB contribute to an autocrine/paracrine amplification loop that mediates the mutual interplay between prostate CSCs and adipocytes." (PMID 26700819, 2016). "Meanwhile, inhibition of CTSB significantly suppressed CCK production by the cancer cells, further supporting that CTSB regulates CCK secretion." (PMID 26700819, 2016). "One of the key pieces of evidence is the stimulation of CTSB secretion by the adipocytes, which in turn further promotes the secretion of CCK by the cancer cells." (PMID 26700819, 2016). "More importantly, we successfully proved that miR-148a directly binds CCK-BR and conduct its anti-cancer effects via inactivating STAT3 and Akt, as well as subsequent modulation of their downstream gene products." (PMID 27518872, 2016). "Further development of the resources presented here should be of high interest in translational research aimed at identifying new targets and biomarkers for treatment and diagnostics of gastrin- and/or cholecystokinin-related disease, including cancer." (PMID 26205660, 2015). "Here we showed a huge increase of CCK mRNA expression in tumors from annexin A1 ko mice, the further study of interaction of annexin A1 and CCK will shed light on understanding the role of CCK in human cancers." (PMID 23077482, 2012). "We also confirmed here that the intraperitoneal injection of sulfated CCK-8 (10 and 30 μg/kg) resulted in an increase in IL-1β production in cancer-inoculated regions." (PMID 20979661, 2010). "In this investigation, we showed that by blocking the CCK-BR signaling pathway, the mRNA expression of specific genes involved in increased collagen deposition in the extracellular matrix, cancer cell proliferation, invasion, and metastases was significantly decreased." (PMID 41373844, 2025). "Given the therapeutic potential of CCK2R in the treatment of cancer, for instance, by grafting of the endogenous CCK-8 sequence into the cyclotide scaffold, and the conjugation of an imaging reagent could yield a high-affinity cancer imaging probe." (PMID 35654807, 2022). "In addition to the acute digestive effects, both gastrin and CCK have been suggested to exert potent proliferative and anti-apoptotic effects by contributing to pathogenesis and progression of cancer." (PMID 32210918, 2020). "In return, CTSB facilitates further CCK secretion by the cancer cells." (PMID 26700819, 2016). "Receptors for peptides secreted by neuroendocrine cells, such as secretin, gastrin, bombesin, cholecystokinin, and vasoactive intestinal peptide, have been identified in many cancer types, including cancers of lung, ovarian, thyroid, brain, genitourinary and gastrointestinal tract." (PMID 24392036, 2013). "To determine whether CCK contributed to the increased levels of IL-1β in the cancer-inoculated region, we examined the effect of sulfated CCK-8 injection on IL-1β production." (PMID 20979661, 2010).
cancer (continued). "However, it should be noted that the CCK2R- and CCK1R-mediated signal transduction varies in the context of cell types, suggesting that cautions should be taken in future investigations attempting to target the gastrin and CCK system for the treatment of certain types of cancer." (PMID 32210918, 2020). "Therefore, exposing the cancer cells to a high lipid content (i.e. high-fat diet or co-culturing with adipocytes) may promote the CCK-autocrine loop and further driven the expansion of prostate CSCs." (PMID 26700819, 2016). "Moreover, we observed that the CCK1 receptor antagonist devazepide similarly suppressed up-regulation of ephrin B1 gene expression and IL-1β production, and that the intraperitoneal injection of sulfated CCK-8 induced the production of IL-1β in the cancer-inoculated region." (PMID 20979661, 2010). "Beyond the impact of CCK on gallbladder function and the observed overexpression of CCKAR in specific cancers, our cellular model may also inform targeted anticancer therapies." (PMID 38013211, 2024). "Gastrin is the major ligand activating the CCK-BR and because PAS therapy induces neutralizing gastrin antibodies and gastrin-activated memory T cells, the ability to decrease signaling at this receptor is central to inhibiting cancer growth." (PMID 34926305, 2021). "More importantly, CCKBR inhibition was found to suppress the promoting effect of adipocytes on spheroid formation of the cancer cells, supporting that adipocytes stimulate prostate CSC self-renewal by facilitating the activation of the CCK/CCKBR autocrine loop." (PMID 26700819, 2016).